BRD4 (bromodomain containing 4)
Diseases named in the same sentence as BRD4 in open-access papers (continued):
Sharing a sentence is not in itself a finding about the gene and the disease.
breast cancer (continued). "We have fully validated the epigenetic screens in vivo and in vitro by analyzing four different hits and we have demonstrated that BAZ1B, BPTF, BRD4 and CHD4 are essential for breast cancer growth." (PMID 27779108, 2016). "Of the known components in the three major P-TEFb-containing complexes, the 7SK snRNP, the Brd4-bound complex, and the SEC, only LARP7 and HEXIM1, two signature components of the 7SK snRNP, showed consistent alteration in human breast cancer tissues." (PMID 25053741, 2014). "Targeting ARID1A phosphorylation pathways, potentially via MAPK inhibitors or BRD4/BRD9 antagonists, could restore its suppressive activity and improve treatment outcomes in breast cancer." (PMID 41572083, 2026). "Additionally, the expression of BRD4 in TNBC is highest among all three subclasses (luminal, HER2 positive, and triple negative) of breast cancer." (PMID 41031256, 2025). "The mRNA level of BRD4 in the HL435-treated group was not lower than that of control group in breast cancer cells, indicating that HL435 did not affect BRD4 at the transcriptional level but rather at the protein level." (PMID 38768083, 2024). "Disruption of Twist-BRD4 interaction by BET-specific inhibitors in vitro and in vivo have been shown to reduce WNT5A expression and inhibit tumorigenicity and invasion of basal-like breast cancer." (PMID 38935814, 2024). "In line with this, Lu and collegues concluded that inhibition of bromodomain-containing protein 4 (BRD4) in TNBC cell lines regulates SNAI1 in a PKD1-dependent manner, resulting in decreased migration and invasion in breast cancer cells and reduced tumor growth and metastasis in xenograft models." (PMID 37293129, 2023). "In breast cancer, BET members differentially regulate an aggressive phenotype with BRD2 as a positive regulator of epithelial-to-mesenchymal transition (EMT) and BRD3 and BRD4 as repressors of this program." (PMID 36982740, 2023). "For the rescue of BRD4-dependent PD-L1 degradation, the PD-L1_GFP expression vector was transfection into breast cancer cells with/without ARV-825 (BRD4 degrader)." (PMID 37924094, 2023). "By taking advantage of the CPTAC proteomics dataset, we stratified breast cancer samples into different breast cancer subtypes and observed that LOXL2 protein levels were significantly increased in each of them, whereas BRD4 only showed a mild increase in TNBC." (PMID 37937685, 2023). "For the second possibility, JQ1 neither displaces BRD4 from chromatin nor alters H3K27ac level in BET inhibitor–resistant breast cancer cells." (PMID 37759202, 2023). "Given the intricate classifications of breast cancer, not all types are responsive to BRD4 inhibitors." (PMID 38099141, 2023). "Additionally, the expression of BRD4 in TNBC is highest among all three subclasses (luminal, HER2 positive, and triple-negative) of breast cancer (p < 0.001)." (PMID 36499487, 2022). "Since ESR1 mutations drive super-enhancer–mediated transcriptional reprogramming in ER+ breast cancer cells, we hypothesized that the transcriptional activity of ESR1 mutants is likewise dependent on BRD4." (PMID 35881485, 2022). "The interaction of Twist and BRD4 at the enhancer and promoter of WNT5A promote the expression of WNT5A, which leads to the activation of WNT signal pathway to accelerate EMT and tumorsphere formation in basal-like breast cancer cells." (PMID 35216622, 2022).
breast cancer (continued). "Proof of principle was provided by degradation of BRD4 only in HER2 positive breast cancer cells but not in HER2 negative background." (PMID 36499765, 2022). "Combined treatment of BRD4 inhibitor and PELI1 inhibitor (BBT-401) may be effective in treating breast cancer." (PMID 35740532, 2022). "In breast cancer, inhibited BRD4 reduces the epithelial–mesenchymal transition (EMT) by decreasing the expression of the snail gene, which further reduces the migration and invasion of breast cancer cells." (PMID 34834420, 2021). "Moreover, analysis of BRD4 expression from GSE7378, GSE9195 and GSE7390 revealed that lower expression of BRD4 predicts prolong survival of breast cancer patients in comparison to high expression of BRD4." (PMID 34803511, 2021). "The bromodomain-containing protein 4 (BRD4), a member of the bromodomain and extra-terminal domain (BET) protein family, has emerged in the last years as a promising molecular target in many tumors including breast cancer." (PMID 33809005, 2021). "Prolong treatment of breast cancer cells with AKT inhibitors (which inhibit AKT phosphorylation) induces dephosphorylation of FOXO3a, nuclear translocation, and destruction of its binding to SIRT6, resulting in FOXO3a acetylation and BRD4 recognition." (PMID 34679680, 2021). "However, other researchers have indicated that BRD4 inhibition decreases RAD51 expression and homologous recombination repair, thus potentially inducing DNA damage in prostate and breast cancer cells." (PMID 32208449, 2020). "JQ1 inhibits BRD3- and BRD4-mediated recruitment of WHSC1 to the ERα gene, thereby suppressing the classic estrogen receptor-α signaling pathway, resulting in the growth suppression of tamoxifen-resistant breast cancer cells in culture." (PMID 30906568, 2019). "The aim of this study was to examine whether combining a novel BRD4 inhibitor, ITH-47, with the antimitotic estradiol analogue, ESE-15-ol, would have a synergistic effect on inhibiting the growth of two different breast cancer cell lines in vitro." (PMID 31886177, 2019). "In this study, we investigated whether a combination of two novel in silico-designed compounds, namely, ITH-47 (BRD4 inhibitor) and ESE-15-ol (an antimitotic agent), would synergistically inhibit the growth of breast cancer cells, MCF-7 and MDA-MB-231." (PMID 31886177, 2019). "Furthermore, high CDK6 protein level is tightly correlated to the recurrence of luminal breast cancer, lending further support to the pro-survival role of CDK6 mediated by the FOXO3a-BRD4 complex in luminal breast cancer." (PMID 30518851, 2018). "Here we demonstrate that the BET bromodomain inhibitor JQ1 exerts growth-inhibitory activity in human luminal breast cancer cell lines associated with a depletion of the C-MYC oncogene, but does not alter the expression levels of the BRD4 bromodomain protein." (PMID 28881673, 2017). "Pharmacological disruption of bromodomain-containing protein 4 (BRD4) binding to Wnt5a promoter by JQ1, a small molecule inhibitor that targets the bromodomain, suppresses EMT, invasiveness, and CSC-like phenotypes in basal-like breast cancer." (PMID 27840647, 2016). "The Brd4 gene expression signature was also able to stratify breast cancer patients with lymph-node-negative and estrogen-receptor-positive at presentation into high- and low-risk patients." (PMID 22295248, 2012). "Maneiro and colleagues demonstrated the specificity of these drugs by creating an antibody–PROTAC conjugate which degraded bromodomain-containing protein 4 (BRD4) specifically in HER2-positive breast cancer cell lines without affecting the BRD4 levels in HER2-negative cells." (PMID 37627229, 2023).
breast cancer (continued). "Overexpression of the epigenetic regulator, BRD4, has been shown to be a negative prognostic indicator in breast cancer, and BET family inhibitors such as ARV-825 and ABBV-744 have garnered interest for their potential to improve and prolong the response to current therapeutic strategies." (PMID 37627092, 2023). "Several BrD members, namely BRPF1, SMARCA4, BRD7, BRD9, BAZ1B, ATAD2 and BRD4 are significantly upregulated in basal breast cancer subtype (when compared to less aggressive luminal A and normal‐like subtype), which strongly mimics the results obtained for the mRNA‐SI." (PMID 35049055, 2022). "We show that combined treatment of JQ1 (inhibitor of BRD4) and NSC23766 (inhibitor of RAC1) suppresses cell growth, clonogenic potential, cell migration and mammary stem cells expansion and induces autophagy and cellular senescence in molecular subtypes of breast cancer cells." (PMID 34803511, 2021). "Furthermore, when comparing expression levels of BET proteins, we found that BRD2 showed higher expression levels compared to BRD3 and BRD4 in the three cell lines, suggesting that BRD2 could be a major target of (+)-JQ1 in canine mammary cancers." (PMID 31758045, 2019). "In this study, we examined if a novel drug, namely, ITH-47, which is a potential BRD4 inhibitor, combined with an antimitotic compound, namely, ESE-15-ol, would synergistically inhibit the growth of tumorigenic MCF-7 and metastatic MDA-MB-231 breast cancer cell lines." (PMID 31886177, 2019). "Further understanding BRD4’s role in different immune contexts may help to identify an appropriate subset of breast cancer patients who may benefit from BET inhibitors without the risk of diminishing the anti-tumoral immune activity." (PMID 30029633, 2018). "Furthermore, gene essentiality data generated for luminal breast cancer cell lines recently uncovered a BET-independent requirement for BRD4, demonstrating that BRD4 knockdown lethality not always coincides with JQ1 sensitivity." (PMID 29760405, 2018). "Disrupting the interaction of BRD4 with Twist1 by using BET-specific inhibitors (such as JQ1) may be a novel approach to indirectly suppress Twist1 function and provide a potential new target for the treatment of basal-like breast cancer." (PMID 28099910, 2017). "Suppression of BRD4 using small compounds such as JQ1, I-BET151 and MS417 has been shown profound efficacy against a wide range of cancers such as diffuse large B cell lymphoma, AML, MLL, non-small cell lung cancer, breast cancer, pancreatic cancer and melanoma." (PMID 25603177, 2015). "We found that the Brd4-P-TEFb complex was also increased moderately upon LARP7 KD (data not shown), suggesting the possibility that Brd4 may also play a role in facilitating the P-TEFb-dependent breast cancer progression." (PMID 25053741, 2014). "At this point it is not known whether the small-molecule inhibition of Brd4 would have any effect on breast cancer and metastatic progression." (PMID 22295248, 2012). "In combination, the selective BRD4 inhibitor, ITH-47, and ESE-15-ol synergistically inhibited the growth of MDA-MB-231 breast cancer cells, but not of the MCF-7 cell line." (PMID 31886177, 2019). "In the breast cancer cell line HeLa, a preferential alteration of Brd4-dependent genes (including MYC, p21, and AREG) but not other Brd4-independent genes (such as FAS, FGFR1, and TYRO3) was induced by MZ1 relative to JQ1, which was consistent with the selective suppression of Brd4 by MZ1." (PMID 37049806, 2023).
prostate carcinoma (111 papers, 2013 to 2026). A carcinoma that arises from epithelial cells of the prostate gland. "BRD4 is a transcriptional and epigenetic regulator that is frequently overexpressed in prostate cancer, particularly CRPC, and associated with aggressive clinical features." (PMID 40163908, 2025). "Loss-of-function mutation of SPOP (BRD4 E3 ubiquitin ligase) in prostate cancer causes impaired ubiquitination-dependent BRD4 degradation, contributing to BETi resistance." (PMID 40650308, 2025). "Prostate cancer-associated SEs are frequently bound and activated by bromodomain-containing protein 4 (BRD4), a transcriptional and epigenetic regulator with a prominent function in prostate cancer progression." (PMID 39117800, 2024). "Transcriptomic and epigenomic approaches revealed that CDKI-73 suppressed signaling pathways regulated by AR, MYC, and BRD4, key drivers of dysregulated transcription in prostate cancer, and reprogrammed cancer-associated super-enhancers." (PMID 39117800, 2024). "The inhibition of BRD4 reduces ROS production in prostate cancer cells, and this effect is associated with the Keap1/Nrf2 signalling pathway." (PMID 37699016, 2023). "For instance, Cullin3SPOP-targeted BRD4 ubiquitination promotes BRD4 protein degradation, while prostate cancer-associated SPOP mutants block this process." (PMID 37737256, 2023). "Of note, the gene encoding the E3 ubiquitin ligase substrate-binding adaptor SPOP is frequently mutated in primary prostate cancer that leads to accumulations of multiple onco-proteins, including BRD4, AR, NANOG, Caprin1, or GLI." (PMID 36357379, 2022). "BRD2 overexpression in cooperation with BRD4 causes chromatin decompaction and androgen receptor activation, which lead to prostate cancer development." (PMID 35401196, 2022). "In clinical tumor samples, BRD4 levels are negatively associated with outcomes after prostate cancer radiation therapy." (PMID 34540900, 2021). "BRD4 protein expression at diagnosis positively associates with a poor overall survival in patients with prostate cancer, and the strength of this association increases as castration-resistant disease develops." (PMID 31901895, 2020). "Most importantly, we identified the functional regulation of BRD4‐AR signaling by miR‐200a, which associates with patient outcomes in aggressive prostate cancer." (PMID 30784214, 2019). "A preferential binding of BRD4 to many SNPs located in enhancers and associated with prostate cancer risk has been reported." (PMID 31200487, 2019). "First studies related to the implication of such super-enhancers in prostate cancer are emerging and the enrichment of the acetyl mark binder bromodomain-containing protein 4 (BRD4) at genetic risk loci has recently been reported." (PMID 28486411, 2017). "AR activity in prostate cancer is also intimately linked to BRD4." (PMID 40163908, 2025). "In prostate cancer, higher nuclear BRD4 protein expression in pre-treatment tumor samples is associated with higher rate of treatment failure in patients receiving RT as a part of primary treatment, suggesting that BRD4 plays an important role in RR10." (PMID 36693944, 2023). "The authors postulated that the two-sided regulatory mechanism of BRD4 might prevent prostate cancer cells from a loss of HMOX1 promoting cell survival during oxidative stress." (PMID 31097977, 2019). "A provocative new finding by Zuber and colleagues with implications in risk assessment shows that tissue-specific SNPs in super-enhancer sequence bound by BRD4 are significantly associated with increased prostate cancer risk and show better enrichment for risk loci than AR." (PMID 29888169, 2018). "In agreement with this, active E2F1/BRD4 transcriptional programs have been identified in prostate cancer cells and cellular data have documented direct effects of BET proteins on E2F1 transcriptional activities." (PMID 41540805, 2026).
prostate carcinoma (continued). "ARV‐771 affects kinase‐dependent oncogenic signaling indirectly by inducing the strong degradation of BRD4, a master regulator of transcriptional programs in AR+ prostate cancer." (PMID 41362117, 2025). "This is the first study demonstrating that BRD4 promotes the collective migration phenotype in prostate cancer through a mechanism dependent on H19." (PMID 40407591, 2025). "Another observation reflecting the intimate association between BRD4, CDK9 and AR in prostate cancer is that cells that have acquired resistance to BRD4 inhibition exhibit adaptive responses to AR and CDK9." (PMID 40163908, 2025). "Taken together, our findings expand the biological role of BRD4 in prostate cancer metastasis and introduce a novel regulatory axis involving H19 as a critical modulator of adhesion gene transcription." (PMID 40407591, 2025). "Bromodomain and extra-terminal domain (BET) proteins, including BRD2 and BRD4, serve as epigenetic acetylation readers that influence tumorigenic signalling in various cancers, including prostate cancer." (PMID 40694184, 2025). "AZD5153 at 40 nM increased the percentage of dead cells, including necrotic and apoptotic, indicating that BRD4 is a primary target in prostate cancer." (PMID 40694184, 2025). "The BET proteins (BRD2/3/4) are key epigenetic co-regulators mainly for prostate cancer growth, with BRD4 being a critical component of AR signaling." (PMID 40407591, 2025). "Through pharmacologically probing the function of epigenetic regulators in prostate cancer cells and organoids, we identified bromodomain protein BRD4 as a crucial player." (PMID 40370549, 2025). "The function of BRD4 in CRPC prostate cancer is relatively well understood which has led to clinical trials of BRD4 inhibitors in treating CRPC patients." (PMID 40370549, 2025). "In prostate cancer, P-TEFb and BRD4 directly interact with the androgen receptor (AR) to mediate expression of important target genes, such as prostate-specific antigen (PSA)." (PMID 39800748, 2025). "Through integrated functional genomics studies, we found that BRD4 drives prostate cancer progression to NEPC by directly activating LP gene programs." (PMID 40370549, 2025). "AR-driven prostate cancer models are preferentially sensitive to BRD4 inhibition, since BRD4 and AR co-localise at target loci, including super-enhancers, to drive AR-mediated gene transcription." (PMID 40163908, 2025). "In prostate cancer cells, bromine domain protein 4 (BRD4) regulates p300 and GCN5 levels to influence histone Kcr." (PMID 39513918, 2024). "Our results provide an additional mechanism to support BRD4 as a potential therapeutic target for prostate cancer." (PMID 39146021, 2024). "Collectively, these data reveal the potential of combining CDKI-73 with a BRD4 inhibitor as a novel treatment for aggressive prostate cancer, including both AR-driven and AR-independent disease states." (PMID 39117800, 2024). "In prostate cancer, BRD4 is most extensively studied, and one of the BRD4-mediated oncogenic mechanisms involves the elevation of key oncogenic drivers like c-Myc, which can substantially contribute to the uncontrolled growth of cancer cells." (PMID 38201308, 2024). "The interconnected functions of CDK9 and BRD4 have led to the evaluation of combinatorial targeting of both factors as a cancer therapy, a concept we explored in prostate cancer." (PMID 39117800, 2024). "Herein, we extend this earlier work by showing significant synergy between CDKI-73 and the BRD4 inhibitor AZD5153 in prostate cancer cell lines and organoid models." (PMID 39117800, 2024). "In castration-resistant prostate cancer (CRPC), AHNAK is a downstream target molecule of BRD4, and knockdown of AHNAK or BRD4 inhibits the migration of prostate cancer cells." (PMID 38033502, 2023). "The conjugates exhibited highly potent BRD4 degradation and antiproliferation activity against prostate cancer cell line PC3-S1 in vitro." (PMID 36770585, 2023).